CRP (C-reactive protein)
Diseases named in the same sentence as CRP in open-access papers (continued):
Sharing a sentence is not in itself a finding about the gene and the disease.
Sepsis (continued). "In addition, based on several previous studies, many inflammatory cytokines (such as CRP) are positively correlated with sepsis risk and appear to be promising indicators for worse prognosis in sepsis patients." (PMID 30803045, 2019). "Even if these CV are lower than the ones, we observed previously for allergy diagnostics, they could have a diagnostic impact: A decrease in CRP of at least 25% compared to the patient’s previous test result is considered a good indicator of sepsis resolution." (PMID 31419260, 2019). "Increased CRP levels in sepsis are associated with worse prognosis." (PMID 31341910, 2019). "The retrospective design and inclusion of all newborns with a late-onset sepsis evaluation may have led to the inclusion of patients with other conditions associated with an increased CRP." (PMID 29382319, 2018). "Myocardial dysfunction during sepsis and pneumonia has been variously associated with increased circulating cytokines and prostanoids, endothelin upregulation, impaired oxygen utilization, and increased levels of C-reactive protein." (PMID 30618794, 2018). "Although the organisms causing late-onset sepsis may be different, CRP responses in early- and late- onset sepsis are similar with potentially more sensitivity for sepsis in late-onset sepsis." (PMID 30509228, 2018). "In addition to early biomarkers of severe inflammation (PCT and CRP), it is important to acknowledge biomarkers of later stages of sepsis indicative of progression to a state of sepsis-associated immunosuppression." (PMID 29104224, 2017). "The diagnostic superiority of PTX-3 over PCT or CRP is still under debate, as different studies so far have been inconsistent regarding their diagnostic capacity in patients with sepsis and septic shock, applying different criteria and definitions of the sepsis syndrome." (PMID 28793880, 2017). "However, the associations between sepsis and Hp, CRP, and SAA remained significant after adjustment for relevant covariates included in final multiple linear regression models (p-values of 0.029, 0.012, and 0.001 respectively)." (PMID 28045978, 2017). "Additionally, the induction of sepsis was observed based on the elevated levels of the sepsis-associated marker C-reactive protein (CRP) and the pro-inflammatory cytokine IL-6 in the circulatory system in pigs with MRSA-infected wounds." (PMID 28177877, 2017). "Our study found that DNI, which reflects the proportions of immature granulocytes in circulating blood, was more accurate than the WBC count, neutrophil percentage, and CRP for predicting mortality of patients undergoing surgical treatment of sepsis caused by peritonitis." (PMID 28763506, 2017). "Notably, miR-25 displayed a superior diagnostic accuracy for sepsis compared to well established markers such as CRP and PCT according to ROC curve analysis." (PMID 26761003, 2016). "Here, we intend to evaluate the diagnostic ability of presepsin in the differential diagnosis including SIRS, infection, or sepsis and to compare its diagnostic value with other markers, mainly as CRP, PCT, and WBC in patients of nephrolithiasis presenting with SIRS." (PMID 25722986, 2015). "Albumin and C-reactive protein (CRP) are considered as good diagnostic markers for sepsis." (PMID 26158725, 2015). "We carried out this study to determine whether PCT and CRP can be diagnostic markers of sepsis or prognostic indicators of mortality of neurotrauma patients." (PMID 24330775, 2013). "In 59 critically ill children, plasma arginine and citrulline levels were lower in patients with sepsis or trauma compared to patients with viral disease and were inversely associated with severity of inflammation as indicated by the plasma C-reactive protein concentration." (PMID 23327349, 2013).
Sepsis (continued). "In recent years, based on the premise that their increase in response to infection may precede that of CRP, the search for diagnostic tests for early-onset sepsis in newborns has led to a consideration of cytokines, alone or in combination with CRP." (PMID 22672862, 2012). "On the sixth postoperative day, following 4 days of leeching, the vascular status of the flap improved, but the patient showed a clinical presentation of septicemia associated with 39.2°C hyperthermia, a white blood cell count of 27,44 109/L and a C-reactive protein (CRP) level increased by 153mg/L." (PMID 23098279, 2012). "This relationship could be explained by the simple fact that CRP reflects the severity of sepsis and the risk of organ failure." (PMID 19538758, 2009). "Patients with sepsis-associated delirium had higher CRP levels (P = 0.008)." (PMID 18457586, 2008). "Cross-sectional study to determine the operative characteristics of three biological markers of inflammation and coagulation (D-dimer, C-reactive protein and Procalcitonin) as diagnostic tests for sepsis, in patients admitted to hospital care with a presumptive infection as main diagnosis." (PMID 18284667, 2008). "Understanding the pattern of change in levels of CRP associated with a particular condition may improve its diagnostic and prognostic value in children with sepsis." (PMID 17598889, 2007). "IL-6, LBP and CRP appear to be superior as diagnostic sepsis markers compared with PCT." (PMID 16569262, 2006). "Our multivariate logistic regression analysis identified several key risk factors for postoperative sepsis, including female gender, age ≥60 years, BMI ≥25 kg/m2, preoperative positive urine culture, and elevated postoperative levels of inflammatory markers (CRP, FPG, and HbA1c)." (PMID 40761819, 2025). "Although presepsin is detectable in healthy subjects at low concentrations, its levels increase rapidly in sepsis, presenting greater sensitivity and diagnostic accuracy for bacterial infections compared to conventional inflammation markers, such as procalcitonin and C-reactive protein (CRP)." (PMID 40149676, 2025). "Therefore, our operational infection criteria could be influenced by CRP levels, which might partly explain the association between higher CRP and sepsis." (PMID 40319081, 2025). "Second, stress responses triggered by ICH may cause leukocytosis and abnormal inflammatory markers, such as elevated C-reactive protein and procalcitonin, which closely resemble diagnostic criteria of sepsis (C-reactive protein>50 mg/L and procalcitonin>0.5 μg/L)." (PMID 40293793, 2025). "Therefore, sTREM-1, IL-6, and lactate should be considered in early sepsis risk assessment, while CRP and PCT may be more beneficial for tracking clinical progression." (PMID 39655134, 2024). "Likewise, while CRP is an acute-phase reaction material that increases with infection or inflammation, it can also rise due to other causes such as trauma, making it an unreliable sepsis severity indicator." (PMID 39767608, 2024). "In addition, CRP (OR 1.021, 95% CI 1.011–1.031, P < 0.001) was a risk factor of sepsis." (PMID 38609858, 2024). "In patients with sepsis, MR-proADM levels were 2.3 nmol/L (0.7–7.8 nmol/L), with the highest values observed in septic shock patients (5.6 nmol/L (3.2–18 nmol/L)) and a better diagnostic profile than procalcitonin and C-reactive protein to identify septic patients." (PMID 37629236, 2023). "Early markers like IL-6 and later markers like CRP are helpful in the diagnosis of neonatal sepsis considering the clinical aspect of the neonate, the gestational age, maternal risk factors and the time (age of the neonate regarding early-onset sepsis) of blood sampling." (PMID 35345614, 2022).
Sepsis (continued). "A large number of inflammatory biomarkers (C-reactive protein, presepsin, procalcitonine, proadrenomedullin, adrenomedullin, kallistatin, etc.)have been studied and were found to be associated with the presence of sepsis, with sepsis severity and sepsis outcomes." (PMID 36470834, 2022). "Furthermore, some studies provide preliminary evidence that in certain settings presepsin may be a superior diagnostic and prognostic biomarker of sepsis compared to the more common biomarkers CRP and PCT." (PMID 34150378, 2021). "Its use in the setting of sepsis has been suggested as being potentially most useful in low- or middle-income countries, as it does not require any extra specific analytical capability or cost outlay, although its diagnostic accuracy does seem to be limited and well below that of CRP." (PMID 32164268, 2020). "CRP levels correlate positively with the risk of organ failure and mortality; hence, monitoring these levels may aid in assessing the response to therapy in patients with sepsis." (PMID 32778146, 2020). "Based on the hypothesis that inflammation in sepsis augments oxidative stress, we also aimed to investigate associations between plasma-free thiol levels and inflammatory biomarkers like C-reactive protein (CRP), calprotectin, and neutrophil gelatinase-associated lipocalin (NGAL)." (PMID 33207555, 2020). "Importantly, an elevated CRP (> 5mg/l) was common 24 h post‐vaccination—CRP levels and neutrophil counts are commonly used as diagnostic markers in suspected sepsis—these findings needs to be taken into consideration when assessing febrile infants following vaccination." (PMID 33210468, 2020). "In addition, a meta-analysis of 21 studies in 6007 patients with pneumonia showed elevated PCT to be linked to death from community-acquired pneumonia, and data from Korea have shown changes in PCT and CRP levels to be associated with outcomes in critically ill patients with sepsis." (PMID 30332466, 2018). "All these characteristics may cause AF in sepsis, althoughincreasing evidence has supported that systemic inflammatory response, perse, is the main contributing factor to AF, with increased serumC-reactive protein (CRP) before the onset of AF24." (PMID 26577719, 2015). "Thus, leptin may be utilized as a potential diagnostic marker of sepsis with a similar efficacy to other markers, such as CRP and PCT." (PMID 24669245, 2014). "Thus, PCT has better diagnostic accuracy for sepsis than CRP or IL-6." (PMID 25460569, 2014). "The aim of this study was to investigate the levels of PCT and CRP that are used as diagnostic markers of sepsis in patients with traumatic brain injury at the time of hospital admission, and to evaluate the prognostic value of these markers related to the severity of injury, sepsis and mortality." (PMID 24330775, 2013). "Therefore, we tested the hypothesis that there is an association between sepsis-associated delirium and the inflammatory response reflected by interleukin-6 (IL-6) and C-reactive protein (CRP)." (PMID 18457586, 2008). "Therefore, we found that PCTwas the second useful diagnostic marker in sepsis after CRP." (PMID 19043563, 2008). "CRP is of weak diagnostic value because of its low specificity; a better understanding of patterns of CRP levels associated with a particular form of infection may improve its usefulness as a sepsis marker." (PMID 17598889, 2007). "Age, sex, body temperature, heart rate, the extent of peritoneal irritation signs, C reactive protein, spread of ascites, and sepsis were included in the final model." (PMID 41488846, 2026). "In baseline characteristics, the statistically significant difference between the two groups was observed in the age, BT, HR, peritoneal irritation signs, CRP, Alb, Cre, spread of ascites, sepsis, and CCI." (PMID 41488846, 2026). "Multivariable logistic regression identified CRP, TT, disease severity, CA and ARDS as independent risk factors for sepsis mortality." (PMID 41588929, 2026).
Sepsis (continued). "The C-reactive protein (CRP)-albumin-lymphocyte (CALLY) index is a novel composite biomarker for sepsis." (PMID 41835671, 2026). "As a result, sex, age, BT, HR, peritoneal irritation signs, CRP, ascites, and sepsis were included in the final model." (PMID 41488846, 2026). "Sub-analysis of 39 CRP-matched pairs (±15 mg/L) and multivariable logistic regression-adjusting for age, sex, sepsis, malignancy, CRP, and comorbidities-were performed." (PMID 41976946, 2026). "Distinguishing postoperative sterile inflammation from early sepsis is clinically challenging because conventional biomarkers such as C-reactive protein (CRP) and procalcitonin lack sufficient specificity." (PMID 42278356, 2026). "Early sepsis detection remains challenging despite biomarker advances, with CRP widely used but PCT emerging as superior for bacterial infections in emergency settings." (PMID 42282342, 2026). "It is standard practice at our Neonatal Intensive Care Unit (NICU) in Pakistan to perform routine Blood Cultures (BLCS) and C-Reactive Protein (CRP) to screen for post-operative sepsis." (PMID 42136778, 2026). "In sepsis, reported sensitivity for CRP ranges from 72% to 92%, with specificity often below 70%, limiting its discriminatory value between infectious and non-infectious systemic inflammation." (PMID 41597433, 2026). "CRP performed poorly at discriminating post-operative sepsis, likely due to physiologic inflammation in post-operative neonates." (PMID 42136778, 2026). "In the multivariable analysis, age, sex, steroid use, CCI, BT, sBP, HR, peritoneal irritation signs, WBC, CRP, Alb, Cre, ascites in CT, sepsis, and time from onset to hospital arrival were included in the first model from univariate analysis." (PMID 41488846, 2026). "Compared to the hypoinflammatory phenotype, these patients developed sepsis earlier, had higher C-reactive protein, leucocyte, fibrinogen, and procalcitonin levels on admission, and more frequently presented with septic shock and nosocomial pneumonia." (PMID 41598714, 2026). "Laboratory evaluation revealed acute prerenal kidney injury and a fulminant inflammatory response (CRP 47.7 mg/dl, leukocytes 16.8 × 103/μl, procalcitonin 4.05 ng/ml), prompting a sepsis work-up and empiric broad-spectrum antibiotics." (PMID 42057970, 2026). "This study established CRP, TT, disease severity, CA and ARDS as independent mortality risk factors in sepsis, with the combined model showing optimal performance." (PMID 41588929, 2026). "Early diagnosis of sepsis still remains a clinical challenge, and conventional biomarkers such as CRP and PCT, while widely used, show limitations in sensitivity and specificity." (PMID 41597433, 2026). "Secondary outcomes included sepsis, intensive care unit admission, urinary tract infection, pneumonia, acute kidney injury, and elevated C-reactive protein levels." (PMID 41939182, 2026). "Although widely used clinical biomarkers such as procalcitonin and C-reactive protein provide some prognostic value, they fail to capture the full complexity and dynamic nature of sepsis." (PMID 40230692, 2025). "Only a limited number of biomarkers are currently used individually for diagnosing sepsis in clinics, such as C-reactive protein (CRP) and procalcitonin." (PMID 41239342, 2025). "The results demonstrated that IL-6, PCT, CRP, IL-8, and NEU% exhibited robust diagnostic value in the diagnosis, differential diagnosis, and prognosis of sepsis." (PMID 40264754, 2025). "Previous sepsis research has largely focused on traditional biomarkers such as procalcitonin, C-reactive protein, IL-6, and TNF-α, which are critical mediators of the early inflammatory response." (PMID 40230692, 2025). "By combining RDW and APACHE II score with PCT, IL-6, CRP, and cystatin C, clinicians can obtain a more comprehensive understanding of both the inflammatory and renal aspects of sepsis." (PMID 41281283, 2025).
Sepsis (continued). "In dogs with sepsis, median CRP concentrations decreased significantly between day 1 and day 3 as well as day 1 and day 4 (D1/D3: p < 0.008; D1/D4: p < 0.008)." (PMID 40607352, 2025). "Fifth, laboratory profiles distinguished the two conditions, with HLH showing lower fibrinogen, platelet count, and neutrophil count, along with higher lymphocyte ratio and triglycerides, whereas severe sepsis exhibited elevated CRP and PCT." (PMID 41321462, 2025). "CRP was also elevated in sepsis compared to non-sepsis (median 95 mg/L, IQR 26–186 and 17 mg/L, IQR 3-69, p < 0.001)." (PMID 40319081, 2025). "This study further explored the combined predictive capabilities of heparin-binding protein (HBP) and C-reactive protein (CRP) in patients with sepsis." (PMID 40568199, 2025). "In the clinical setting, commonly used biomarkers to assess sepsis include C-reactive protein (CRP), procalcitonin (PCT), and serum lactate." (PMID 40362448, 2025). "This study demonstrates the potential diagnostic utility of a Bayesian network model integrating soluble myeloid trigger receptor-1, C-reactive protein, and leukocyte count to identify postoperative sepsis in pediatric patients." (PMID 40806505, 2025). "This device removes live bacteria, endotoxins and C-reactive protein from the serum of sepsis patients." (PMID 41145817, 2025). "Our discovery of CRP as a plasma receptor for many bacterial capsules also explains why these types of bacteria show the LV phenotype in mouse sepsis models in our previous studies." (PMID 41214213, 2025). "In our case, the neonate was delivered preterm, showed signs of respiratory distress and possible sepsis, leukocytosis, and high CRP, and her mother had a history of contact with animals in an endemic area." (PMID 40161139, 2025). "A cut-off value of 831 ng/mL was identified and CRP demonstrated a sensitivity of 82% and a specificity of 75% for sepsis prediction (p = 0.006)." (PMID 41011807, 2025). "This study aims to identify and validate key biomarkers for sepsis, addressing the limitations of current diagnostic methods like the SOFA score, PCT, and CRP, particularly in terms of specificity and early detection." (PMID 41472734, 2025). "BUN, sepsis, eGFR, blood uric acid, SCr, CRP, HE, TBIL, age, and INR were significant predictors of RF and XGBoost algorithms." (PMID 41844384, 2025). "Several biomarkers have been explored for their prognostic value in sepsis, including C-reactive protein (CRP), albumin, and lymphocyte count." (PMID 40310418, 2025). "MAP, CVP, SOFA score, vasoactive drug treatment, VIS, CRP, PCT, lactate, BNP, RRI at T1, and RRI reduction were associated with AKI in sepsis cases." (PMID 39864312, 2025). "From November 2022 to November 2023, we prospectively enrolled 100 consecutive outborn neonates (<28 days) with suspected sepsis (positive sepsis screen: ≥2 parameters, e.g., C-reactive protein, leukocyte count) at a tertiary care hospital." (PMID 40462787, 2025). "Although CRP is widely used in this setting and is considered one of the earliest biomarkers for sepsis, it has low sensitivity (ranging between 30 and 97.2%) and specificity (between 75 and 100%) (Morley and Kushner, 1982)." (PMID 39857101, 2025). "In our study, patients with severe forms of the disease had significantly elevated CRP levels, with 71.88% of deceased patients with sepsis exhibiting CRP values greater than 100 mg/L." (PMID 40564087, 2025). "The fabricated TFEswere employed in a biosensing experiment for the detection of C-reactiveprotein (CRP), a critical biomarker for sepsis, to evaluate theirperformance." (PMID 41244407, 2025). "This prospective observational study demonstrated that PCT is a significantly more reliable and earlier indicator of postoperative sepsis than CRP or IL-6 in patients undergoing lung decortication." (PMID 41281040, 2025). "Serum levels of Gal-9, sTREM-1, sCD25, and CRP (p < 0.001) were higher in sepsis than in those with NIOF." (PMID 41225969, 2025).